TMPRSS2 (transmembrane serine protease 2)
Diseases named in the same sentence as TMPRSS2 in open-access papers (continued):
Sharing a sentence is not in itself a finding about the gene and the disease.
COVID-19 (continued). "In contrast, the presence of a mutational T-allele of the TMPRSS2 gene (rs12329760) in the genotype increases the likelihood of the disease by more than 2 times, which confirms the role of the TMPRSS2 gene in increasing the likelihood of the clinical development of COVID-19." (PMID 40573382, 2025). "Variations in the genetic makeup of TMPRSS2 could be responsible for the disparities in COVID-19 severity found across different groups of people, suggesting that people carrying specific TMPRSS2 variants may have a higher risk of experiencing severe health consequences." (PMID 40297833, 2025). "Furthermore, genetic investigations demonstrate that TMPRSS2 expression levels could vary across populations in general, influencing susceptibility to COVID-19; however, these outcomes require further investigation." (PMID 40297833, 2025). "Therefore, as the portal of virus invasion, the low expression of ACE2 in respiratory epithelial cells of AR patients can reduce the possibility of infection and deterioration of COVID-19 in AR patients, thus counteracting the potential adverse consequences caused by the increase in TMPRSS2." (PMID 39057037, 2024). "The rs12329760 polymorphism in TMPRSS2 may explain different genetic susceptibilities to COVID-19." (PMID 38263160, 2024). "Consequently, this information may prove valuable in elucidating the significance of the TMPRSS2 rs2070788 polymorphism concerning susceptibility and severity of COVID-19." (PMID 39188881, 2024). "Therefore, the study of polymorphisms in ACE2 and TMPRSS2 in various populations could open the way for precision medicine and individualized COVID-19 treatment plans." (PMID 38263160, 2024). "Furthermore, we also found that ACE2, MX1 and TMPRSS2 TAA could work as a protective role contrasting with CAA significantly associated with an increased risk of developing severe COVID-19." (PMID 37287057, 2023). "Recent studies indicate that individuals who identify as male are at a higher risk of mortality from COVID-19, possibly due to androgen-mediated regulation of the transmembrane protease serine 2 (TMPRSS2) and ACE-2, which could facilitate the entry and replication of SARS-CoV2." (PMID 37916248, 2023). "We also hypothesize that patients with Down syndrome might be more susceptible to poor COVID-19 outcomes because the TMPRSS2 gene, a serine protease for SARS-CoV-2 spike protein priming for viral host cell entry, is located on the 21q22.3 gene, a critical part of the Down syndrome region." (PMID 36573520, 2023). "Since May 2020, when we reported the TMPRSS2 variant rs12329760 as possibly damaging to protein structure/function and raised the possibility that it could partly explain host susceptibility to COVID-19 severity, several other studies have also supported this hypothesis." (PMID 35104687, 2022). "Additionally, miRNAs associated with ACE2 and/or TMPRSS2 expression may also serve as potential targets for COVID-19 therapeutic applications." (PMID 36293144, 2022). "In this study, we hypothesized that ACE2 and TMPRSS2 may be influencing progression of COVID-19 disease, while various genetic patterns may be affecting the risk of infection, viral invasion, aggressiveness, and mortality rates of COVID-19." (PMID 35193695, 2022). "Overall, polymorphisms in ACE2 and TMPRSS2 genes influence susceptibility, symptoms, and severity of patients to COVID-19 among populations across different regions of the world, suggesting that these genes could be potential targets in development of treatment therapies for COVID-19." (PMID 35193695, 2022). "Furthermore, men who are carriers of TMPRSS2 gene mutations, which potentiate androgen-induced cellular expression of TMPRSS2, may be especially at risk for COVID-19 morbidity and mortality." (PMID 35602518, 2022).
COVID-19 (continued). "However, it remains unknown whether TMPRSS2 mutation affects COVID-19 severity, thereby indicating the need for additional studies to understand the causation roles of TMPRSS2 mutation in COVID-19." (PMID 36364238, 2022). "ACE2 and TMPRSS2 levels were higher at resection margins of lung cancer survivors than those in normal tissues of non-cancerous individuals and may serve as factors responsible for the high susceptibility to COVID-19 among lung cancer survivors." (PMID 34094930, 2021). "TMPRSS2 can be regulated by androgen and its receptor and the presence of AREs on the promoter of the TMPRSS2 gene may be the underlying cause of the severity and higher mortality of COVID-19 in men." (PMID 34527703, 2021). "However, whether sex hormones-dependent modulation of ACE2 or TMPRSS2 in the lung or other SARS-CoV-2 target tissues correlates with COVID-19 susceptibility or severity needs to be further elucidated." (PMID 34925228, 2021). "At the same time, polymorphisms of the ACE-2 and TMPRSS2 genes are more common among Africans and Europeans, facilitating easier penetration of the virus into the cell, which may explain the differential genetic predisposition to COVID-19." (PMID 33802310, 2021). "Also TMPRSS2 variants and resulting expression influence COVID-19 severity." (PMID 34016183, 2021). "Since the early days of the pandemic coronavirus disease 2019 (COVID-19) started from the Chinese city of Wuhan, Hubei province, in December 2019, many reports highlighted the crucial role of transmembrane serine protease 2 (TMPRSS2) in the spread and progression of the viral infection." (PMID 33996911, 2021). "Therefore, the difference in ACE-2 and TMPRSS2 expression between the sexes may be associated with the severity or prognosis of COVID-19 patients." (PMID 33374452, 2020). "Therefore, the occurrence of specific comorbidities associated with RAS imbalance mediated by ACE2/ADAM17 along with specific genetic factors mainly associated with TMPRSS2 expression could be decisive for the clinical outcome of COVID-19." (PMID 33117379, 2020). "Furthermore, COVID-19 involves an olfactory abnormality, and it has been reported that ACE2 and TMPRSS2 expression in olfactory epithelial supporting cells and stem cells may be involved in the mechanism underlying the olfactory abnormality in COVID-19." (PMID 32825469, 2020). "The mucolytic agent, bromhexine, a transmembrane serine protease 2 (TMPRSS2) inhibitor, has also been proposed for COVID-19 therapy." (PMID 41601977, 2026). "In an in vitro experiment with blood samples from patients with COVID-19, platelet expression of ACE2 receptor and TMPRSS2 was associated with platelet activation, platelet aggregation, PAC-1 binding, P-selectin expression, and clot retraction." (PMID 39179952, 2025). "We show that a broad serine protease inhibitor that underwent clinical trials for TMPRSS2-targeted COVID-19 therapy, nafamostat mesylate, was rapidly cleaved by TMPRSS11D and converted to low activity derivatives." (PMID 40348740, 2025). "For this study, we selected camostat, a well-known serine protease inhibitor that blocks TMPRSS2 and has been explored as a potential antiviral drug against COVID-19." (PMID 40143232, 2025). "The IFN-mediated increase in PD-L1 expression represents a form of “adaptive resistance”, which we demonstrated in our results with an upregulation of IFN and PD-L1 in cells with high TMPRSS2 expression and in COVID-19 patients." (PMID 40055791, 2025). "The significant contribution of TMPRSS2 to enhancing SARS-CoV-2 infectivity highlights its pivotal role in COVID-19 pathogenesis." (PMID 40724833, 2025). "TMPRSS2 showed a significant decrease in levels in patients with mild COVID-19 compared to healthy individuals, while patients with severe COVID-19 showed intermediate values." (PMID 40003732, 2025).
COVID-19 (continued). "From a genetic viewpoint, several single studies have investigated the association of different single nucleotide polymorphisms (SNPs) of ACE1 (e.g., rs1799752), ACE2 (e.g., rs2285666), or TMPRSS2 (e.g., rs12329760) genes with the severity of COVID-19." (PMID 40076720, 2025). "Administration of the antiviral drug GS-5734 (remdesivir) and anti-inflammatory therapy reduce the blood level of TMPRSS2 in moderate-course and of IL-6 in severe-course COVID-19." (PMID 40573382, 2025). "A correlation analysis between TMPRSS2 and PD-L1 in peripheral blood mononuclear cells (PBMNCs) from COVID-19 patients and healthy controls revealed a positive correlation (R = 0.54; p = 7.2e-08)." (PMID 40055791, 2025). "The overall findings on ACE2 and TMPRSS2 expression levels suggest potential therapeutic approaches for COVID-19 patients." (PMID 40724833, 2025). "This complex genetic landscape helps explain the observed differences in TMPRSS2 genotype distributions between patients with mild and severe COVID-19." (PMID 39858469, 2025). "Recognizing the biochemical mechanisms and structural interactions of TMPRSS2 with the S protein highlights its possibility as a therapeutic target against COVID-19 and other viruses that employ similar entry pathways." (PMID 40297833, 2025). "Previous studies have found significant differences in allele frequencies in the ACE2 and TMPRSS2 genes (receptor and coreceptor genes for SARS-CoV-2, respectively) between patients with COVID-19 and the general population." (PMID 40573382, 2025). "The androgen-dependent regulation of TMPRSS2 and the male predominance in COVID-19 mortality have prompted investigations into androgen-targeted interventions as potential therapeutic strategies." (PMID 41150771, 2025). "A meta-analysis revealed that polymorphisms in the ApoE, ACE1, TMPRSS2, CCR5, and HLA loci seem to influence susceptibility to and/or the severity of COVID-19." (PMID 40142738, 2025). "Antiviral drug GS-5734 (remdesivir) administration with anti-inflammatory therapy reduces the TMPRSS2 blood level in moderate COVID-19, IL-6 in severe COVID-19 course, and fibrinogen A- and D-dimers in both groups." (PMID 40573382, 2025). "These protective mechanisms encompass several factors: the baseline expression of cell surface receptor ACE2 and hydrolase TMPRSS2, the impact of complications on COVID-19, and age-related cytokine profiles." (PMID 40370452, 2025). "Preventing SARS-CoV-2 entry into lung cells by inhibiting TMPRSS2, the host cell activator, and the observed therapeutic effects of camostat mesylate in critically ill COVID-19 patients indicate promising treatment directions." (PMID 40724833, 2025). "It is clinically relevant to consider the organ distribution and abundance of ACE2 and co-factor transmembrane serine protease 2 (TMPRSS2) with age and sex and how COVID-19 affects enzyme activity and subsequently peptide products ANGII and Ang1–7." (PMID 40631549, 2025). "This case illustrates a unique sequence in which COVID-19-related prostatitis was followed by the diagnosis of prostate cancer in a patient with a TMPRSS2::ERG gene fusion." (PMID 41267989, 2025). "Phytopharmaceuticals inhibiting TMPRSS2 and furin demonstrate potential in treating COVID-19 by preventing SARS-CoV-2 entrance and replication, lowering fatality rates." (PMID 40297833, 2025). "Due to its in vitro inhibition of TMPRSS2, nafamostat and camostat were explored as COVID-19 therapeutics in clinical trials." (PMID 40348740, 2025). "In the case of COVID-19, polymorphisms in ACE2 and TMPRSS2 significantly influence susceptibility to SARS-CoV-2 infection and its downstream effects on pulmonary vasculature." (PMID 39997467, 2025). "The highest probability of moderate and severe COVID-19 clinical forms developing was found in G-allele carriers (especially the GG genotype) of the FGB gene (rs1800790) and the T-allele of the TMPRSS2 gene (rs12329760)." (PMID 40573382, 2025).
COVID-19 (continued). "While the consequences of eQTLs on disease susceptibility are substantial, greater study is required to understand how genetic variation affects TMPRSS2 expression and COVID-19 results in distinct populations." (PMID 40297833, 2025). "COVID-19 positive decedents showed strong ACE2 / TMPRSS2 expression in capillaries and less in arterioles/venules." (PMID 39179952, 2025). "Another study involving 609 COVID-19 patients confirmed by RT-PCR and 291 SARS-CoV-2-negative individuals, identified four TMPRSS2 gene polymorphisms (rs12329760, rs2298659, rs456298, and rs462574) as contributing to disease severity and mortality." (PMID 39858469, 2025). "Their analysis of COVID-19 autopsy specimens revealed higher viral infection rates in TMPRSS2-expressing cells, further supporting its role in the viral pathogenesis." (PMID 41150771, 2025). "It has been reported that TB increases the expression levels of Ace2 (angiotensin converting enzyme 2) and Tmprss2 (transmembrane protease serine 2) proteins, which are essential for COVID-19 pathogenesis." (PMID 40196114, 2025). "TMPRSS2, a transmembrane serine protease, has become a promising therapeutic target due to its significant role in various disorders, notably COVID-19." (PMID 40297833, 2025). "Co-expression of ACE2 and TMPRSS2 has been detected using scRNA-Seq in human ovarian tissue, indicating the potential for COVID-19 to affect ovarian function." (PMID 40957873, 2025). "Two recent studies investigated the association between five COVID-19 associated SNPs in AC1, ACE2 and TMPRSS2 and long term post-COVID symptoms in previously hospitalized COVID-19 survivors." (PMID 40692561, 2025). "The levels of TMPRSS2 and ACE2, which are primarily expressed in bronchial transient secretory cells, are associated with the clinical outcomes of COVID-19 patients." (PMID 40297833, 2025). "TMPRSS2 is a target for prospective therapeutic interventions against COVID-19 as it is an essential part of several biological processes, including viral entry by priming the S protein of viruses like SARS-CoV and SARS-CoV-2, crucial for their infectivity." (PMID 40297833, 2025). "RNAseq data from PBMNCs collected from 24 healthy individuals and 62 COVID-19 patients (COVID19db ID: COVID000010) revealed increased levels of TMPRSS2 mRNA in PBMNCs after SARS-CoV-2 infection." (PMID 40055791, 2025). "Next, probing of uEVs from male patients with COVID-19 for TMPRSS2 revealed three distinct protein bands at 54 kDa, 37 kDa, and 18 kDa with the 54 kDa being the weakest." (PMID 39382598, 2025). "Endothelial cells are known to be susceptible to SARS-CoV-2, and the roles of angiotensin-converting enzyme 2 (ACE2) and transmembrane serine protease 2 (TMPRSS2) are key to understanding the vascular complications of COVID-19." (PMID 41516301, 2025). "On the other hand, reports on geographically and ethnically close populations demonstrated the association of TMPRSS2 rs12329760 and ACE2 rs2285666 SNVs with COVID-19 disease severity, highlighting the importance of population-specific studies." (PMID 38855114, 2024). "Genetic variants of furin, TMPRSS2, and ACE2 are all present in the human population at significant levels, and several studies have found that these variants have an impact on COVID-19 presentation." (PMID 38932275, 2024). "There was a greater concentration of TMPRSS2 in the urine of the COVID-19-positive participants compared to the control group." (PMID 39861814, 2024). "The study showed a substantial difference between the mild and severe COVID-19 patient groups regarding their TMPRSS2 (p.Val197Met) genotypes (P value = 0.046)." (PMID 38254046, 2024). "SARS CoV-2, the causative agent for the ongoing COVID-19 pandemic, it enters the host cell by activating the ACE2 receptor with the help of two proteasesi.e., Furin and TMPRSS2." (PMID 38570613, 2024).
COVID-19 (continued). "Camostat mesylate, an oral serine protease inhibitor, is a powerful TMPRSS2 inhibitor and has been reported as a possible antiviral treatment against COVID-19." (PMID 39030491, 2024). "This suggests that TMPRSS2, testosterone, and aromatase can be used as markers of poor prognosis or increased disease severity in COVID-19 hospitalized patients." (PMID 39449074, 2024). "Specifically, our results indicate that female carriers of both major A alleles of TMPRSS2 rs2070788 and at least one minor G allele of ACE2 rs2106809 have lower odds of severe COVID-19 and fatal outcome, respectively." (PMID 39744525, 2024). "We identified two genetic variants out of seven with a statistically significant difference in allelic frequency distribution among COVID-19 patients, corresponding to rs2070788 (P=0.003) and rs7560375 (P=0.04) of the TMPRSS2 gene." (PMID 38601158, 2024). "The genotypic and allelic frequencies among the COVID-19 groups were assessed for each TMPRSS2 (rs2070788, rs75603675, rs12329760) and SERPINE1 (rs2227631, rs2227667, rs2070682, rs2227692) polymorphism (Supplementary 1)." (PMID 38601158, 2024). "The role of TMPRSS2 in COVID-19 is further confirmed by the fact that TMPRSS2 inhibitors approved for clinical use (such as camostat mesylate—a drug used in the treatment of chronic pancreatitis) can block SARS-CoV-2 virus infection." (PMID 39744525, 2024). "In taste buds, the expression of ACE2 and TMPRSS2 in COVID-19 cells was higher than that in the control group." (PMID 38975331, 2024). "TMPRSS2 gene expression is one of the potential mechanisms explaining the difference in COVID-19 severity in males versus females." (PMID 38263160, 2024). "Our findings indicate TMPRSS2 rs2070788 and ACE2 rs2106809 polymorphisms as independent predictors of severity and outcome of COVID-19 in females." (PMID 39744525, 2024). "The concentration of C-reactive protein, transmembrane serine protease 2, and klotho protein were significantly greater in the urine of COVID-19-positive participants." (PMID 39861814, 2024). "This study is the first to examine the potential correlation between the genetic factor TMPRSS2 rs2070788 SNP and COVID-19 severity in multiple predominant cities across Iran." (PMID 39188881, 2024). "The connection of the TMPRSS2 gene variation with COVID-19 severity was investigated in several pieces of research, although the findings needed to be more consistent." (PMID 38254046, 2024). "Associations between COVID-19 severity and single nucleotide polymorphisms of the ACE2 and TMPRSS2 genes, Faculty of Medicine, Zagazig University, Zagazig, Egypt, 01 July 2021 – 30 November 2021." (PMID 39228902, 2024). "The precise functional mechanism through which the rs2070788 SNP, located in the noncoding region of the TMPRSS2 gene, influences the outcome of COVID-19 remains uncertain and necessitates additional research." (PMID 39188881, 2024). "There is a study on the pathogenesis of COVID-19 that reports that there is an interaction between TMPRSS2 and TMPRSS4 in small intestinal epithelial cells." (PMID 39350850, 2024). "For example, the TMPRSS2 inhibitors camostat and nafamostat had been approved for the treatment of pancreatitis in Japan and were repurposed for a potential treatment of COVID-19 since they efficiently block SARS-CoV-2 Spike cleavage in vitro." (PMID 38543698, 2024). "In response to the COVID-19 pandemic, several research groups independently showed that Serpin A1 reduces TMPRSS2-mediated SARS-CoV-2 infectivity." (PMID 38543698, 2024). "Among all individuals carrying TMPRSS2 rs2070788 genotypes, the IL-6 levels exhibited a significant elevation within the COVID-19 group when contrasted with the control group." (PMID 39188881, 2024).